CCDC6 (coiled-coil domain containing 6)
Diseases named in the same sentence as CCDC6 in open-access papers (continued):
Sharing a sentence is not in itself a finding about the gene and the disease.
embryonal carcinoma (1 paper, 2021). A non-seminomatous malignant germ cell tumor characterized by the presence of large germ cells with abundant cytoplasm resembling epithelial cells, geographic necrosis, high mitotic activity, and pseudoglandular and pseudopapillary structures formation. "In embryonal carcinoma and in the testicular cells, following exposure to the oxidative damage, we report that the loss of CCDC6 determined tolerance to reactive oxygen species affecting apoptosis and ferroptosis." (PMID 34841108, 2021). "Strikingly, the transient CCDC6 silencing in GC-1 and in NTERA-2 embryonal carcinoma cells, resulted associated with an increase of xCT/SLC7A11 at mRNA and protein level." (PMID 34841108, 2021). "Appreciable levels of CCDC6 and USP7 proteins were detected in NTERA-2 human Embryonal Carcinoma and in the murine GC-1 spermatogonia cells, while nearly undetectable amount was observed in GC-2 spermatocytes and TM4 Sertoli cells." (PMID 34841108, 2021).
fibrosarcoma (1 paper, 2022). A malignant mesenchymal fibroblastic neoplasm affecting the soft tissue and bone. "However, among confirmed fusions, the concordance in both genes’ expression level was detected only for CCDC6-RET in the fibrosarcoma FS1 sample." (PMID 36009413, 2022).
gastric cancer (1 paper, 2022). A primary or metastatic malignant neoplasm involving the stomach. "Still, their online Kaplan-Meier analysis showed that the patients with gastric cancer and high CCDC6 expression had shorter OSs after chemotherapy." (PMID 36186907, 2022). "Moreover, a significantly positive correlation between CCDC6 gene expression levels and the microsatellite instability (MSI) score was also reported for gastric cancer." (PMID 36186907, 2022).
hepatobiliary tumors (1 paper, 2022). "Interestingly, we found associations between CCDC6 and hepatobiliary tumors using integrative bioinformatics analysis tools as well as immunohistochemical (IHC) detection." (PMID 36186907, 2022). "On the basis of the tight correlation between CCDC6 expression and hepatobiliary tumors, especially HCC, we conducted the following investigations on different online databases." (PMID 36186907, 2022).
intrahepatic cholangiocarcinoma (1 paper, 2021). A carcinoma that arises from the intrahepatic bile duct epithelium in any site of the intrahepatic biliary tree. "Further study exerted that CCDC6 was a predicted target of miR-19b-3p, and in vivo study displayed that miR-19b-3p/CCDC6 axis modulated EMT to promote intrahepatic cholangiocarcinoma development." (PMID 34299149, 2021).
large-cell neuroendocrine pancreatic carcinoma (1 paper, 2024). "This case report describes the efficacy of selpercatinib, a selective RET inhibitor, in an unusual case of large-cell neuroendocrine pancreatic carcinoma (LCNEPAC) harboring a CCDC6::RET fusion." (PMID 39085487, 2024).
leukemia (1 paper, 2018). A malignant (clonal) hematologic disorder, involving hematopoietic stem cells and characterized by the presence of primitive or atypical myeloid or lymphoid cells in the bone marrow and the blood. "In leukemia, CCDC6 rearranged with PDGFRβ contributes an aminoterminus portion of 368 aminoacids." (PMID 29455670, 2018). "CCDC6 has been involved in different rearrangements with several tyrosine kinases (RET, PDGFRb, ROS1, FGFR2) in several tumours (thyroid, lung, leukemia, breast, iCCA)." (PMID 29455670, 2018).
metastatic colorectal cancer (1 paper, 2015). "Through comprehensive genomic profiling we prospectively identified 6 RET fusion kinases, including two novel fusions of CCDC6-RET and NCOA4-RET, in metastatic colorectal cancer (CRC) patients." (PMID 26078337, 2015).
multinodular goiter (1 paper, 2023). Nodular goiter characterized by more than one discrete tissue mass. "Results from qRT-PCR showed the absence of CCDC6::RET or NCOA4::RET rearrangements in normal tissues (n = 10) and benign (multinodular goiter, n = 10) cases." (PMID 37188126, 2023).
myeloproliferative disorder (1 paper, 2012). A clonal hematopoietic stem cell disorder, characterized by proliferation in the bone marrow of one or more of the myeloid (i.e., granulocytic, erythroid, megakaryocytic, and mast cell) lineages. "In most cancers harboring Ccdc6 gene rearrangements, like papillary thyroid tumors or myeloproliferative disorders, the product of the normal allele is supposed to be functionally impaired or absent." (PMID 22363533, 2012).
neuroendocrine tumor (1 paper, 2017). "Moreover, we have observed a lethal effect combining the inhibitors of USP7 and PARP enzymes in lung neuroendocrine tumor expressing USP7 and CCDC6 proteins." (PMID 28415632, 2017).
ovarian tumour (1 paper, 2022). "Although the CCDC6 staining data on PDXs do not discriminate a primary from a resistant ovarian tumour model, we may hypothesise, based on in vitro evidence, that the CCDC6 positive staining could otherwise predict the response to PARPi, as described in other tumour models." (PMID 35964058, 2022).
skin cutaneous melanoma (1 paper, 2022). "The CCDC6 expression levels in skin cutaneous melanoma are also lower than those in the corresponding metastatic lesions (p<0.001)." (PMID 36186907, 2022).
testicular cancer (1 paper, 2021). A primary or metastatic malignant neoplasm that affects the testis. "In the future, a better understanding of the mechanisms which associate CCDC6 with ferroptosis could provide references for novel potential targets to use in the treatment of testicular cancers." (PMID 34841108, 2021). "Notably, the CCDC6 deficiency, which associates with an impairment of the HR DNA DSBs repair, determined PARP inhibitor sensitivity in testicular cancer models." (PMID 34841108, 2021).
testicular tumours (1 paper, 2021). "Strikingly, here we report that in testicular tumours the CCDC6 deficiency specifically associated to impairment of homologous recombination of DNA DSBs which associates to PARP inhibitors sensitivity." (PMID 34841108, 2021). "At immunohistochemistry (IHC) the evaluation of a pilot subset of primary testicular tumours, revealed that CCDC6 staining inversely correlated with the xCT/SLC7A11 expression levels, supporting our in vitro evidence." (PMID 34841108, 2021).
testis (1 paper, 2021). "Appreciable amount of CCDC6 was also detected at western blot in the NTERA-2 cells, a human cellular model of testis Embryonal Carcinoma." (PMID 34841108, 2021).
testis Embryonal Carcinoma (1 paper, 2021). "In a human cellular model of testis Embryonal Carcinoma, the deficiency of CCDC6 was associated with defects in DNA repair via homologous recombination and sensitivity to PARP1/2 inhibitors." (PMID 34841108, 2021).
urothelial bladder carcinomas (1 paper, 2019). "The results presented here are in support of the use of PARP-inhibitors for the treatment of primary urothelial bladder carcinomas that exhibit low levels of CCDC6 protein, as detected in 30% of primary BC of our analysis." (PMID 30786932, 2019). "The pharmacological inhibition of the deubiquitinase enzyme USP7 has shown antitumor properties in several tumor types and also determined cytotoxic effects in a series of urothelial bladder cancer cells expressing appreciable levels of CCDC6 and USP7 proteins at western blot." (PMID 30786932, 2019). "Finally, the identification of two G3 clusters, that allow the stratification of the high-grade bladder urothelial cancer on the basis of CCDC6 expression levels, could help to design personalized treatment by combining all these drugs." (PMID 30786932, 2019). "In this investigation our aim has been to analyse CCDC6 and USP7 expression levels in a series of primary urothelial bladder cancer, arranged in a Tissue Micro Array (TMA), by immunohistochemistry." (PMID 30786932, 2019).
tumor (51 papers, 2012 to 2026). "Other groups indicated that aberrant activation of CCDC6 as an independent gene has been implicated in promoting tumour progression in multiple malignancies, including lung, gastric and bladder urothelial carcinoma." (PMID 41035371, 2025). "In fact, previous studies indicated that the loss of function of the CCDC6 gene confers resistance to cisplatin and sensitizes tumor cells to PARP inhibitors." (PMID 39684377, 2024). "CCDC6 is a tumour suppressor protein known to be functionally lost due to gene translocations, somatic mutations, and altered protein levels, in several tumours." (PMID 35964058, 2022). "High expressions of CCDC6 were significantly associated with clinical severity variables (especially with advanced cancer stages and pathological tumor grades) and poor prognoses in patients with HCC." (PMID 36186907, 2022). "The over expressions of CCDC6 were found to be significantly associated with clinical parameters (especially in clinical cancer stages and pathological tumor grades) and poor prognosis of HCC patients." (PMID 36186907, 2022). "In conclusion, our results revealed that over expressions of CCDC6 is significantly associated with clinical cancer stages and pathological tumor grades in patients with HCC." (PMID 36186907, 2022). "CCDC6 is known to be functionally lost upon gene translocations, somatic mutations, and altered protein levels in several tumours." (PMID 34841108, 2021). "CCDC6 is known to be functionally impaired upon gene fusions, somatic mutations, and altered protein turnover in several tumours." (PMID 34841108, 2021). "CCDC6 is an oncoprotein, of which deficiency affects DNA damage and repair processes and sensitizes tumor cells to the treatment of PARP inhibitors (like olaparib)." (PMID 33967786, 2021). "In some cases, cancer cells carrying the rearranged allele of CCDC6 also show the loss of the unrearranged allele which is suggestive of a suppressive role of CCDC6 in tumor progression." (PMID 31877762, 2019). "USP7, besides AR, has different substrates including PTEN and CCDC6, a tumor suppressor protein whose deficiency affects DNA repair mechanism by homologous recombination and sensitizes tumor cells to PARP inhibitors treatment." (PMID 28415632, 2017). "In primary tumours, the impaired function of CCDC6 protein has been ascribed to CCDC6 rearrangements and to somatic mutations in several neoplasia." (PMID 25885523, 2015). "Finally, we assessed associations between CCDC6 and marker genes of tumor-infiltrated immune cells in HCC to confirm some of our findings." (PMID 36186907, 2022). "Therefore, we further investigated the distinctive genomic alterations and functional networks associated with CCDC6 expression and evaluated its role in tumor targeted therapy and immunotherapy." (PMID 36186907, 2022). "In these cell systems we focused our attention on CCDC6, a tumour suppressor gene, involved in apoptosis and in DNA damage response, and known to be functionally lost upon gene translocations, somatic mutations and altered protein levels in several tumours." (PMID 34841108, 2021). "Loss of CCDC6 has been suggested to contribute to testicular neoplastic growth and could enhance tumour progression by impairing apoptosis following DNA damage." (PMID 32580154, 2020). "Thus, cancer cells that carry the CCDC6 missense mutations, truncation, or fusions are prone to accumulate errors in DNA repair process with a genome instability that can promote tumor progression, leading to radio and chemoresistance." (PMID 31877762, 2019).
tumor (continued). "Overall, our data suggest that in primary tumours the loss of CCDC6 function could influence genome stability and thereby contribute to carcinogenesis." (PMID 22655027, 2012). "Thus, CCDC6 is an attractive candidate biomarker whose loss or inactivation could enhance tumor progression by impairing apoptosis thereby favoring cell survival and allowing the cells to overcome the barrier of a DNA damage response." (PMID 25885523, 2015). "In vivo xenograft and metastasis models confirmed that CCDC6 depletion significantly reduced tumour burden and lung metastases." (PMID 41035371, 2025). "In this study, we confirmed that reducing CCDC6 expression exogenously using P5091 reverses iCCA tumour resistance to gemcitabine." (PMID 41035371, 2025). "To investigate the effects of CCDC6 knockdown on iCCA progression in vivo, we established a subcutaneous tumour formation model (N = 6) and a tail vein tumour cell injection model (N = 5) in nude mice using NC‐HuCCT1 and KD‐HuCCT1 cell lines." (PMID 41035371, 2025). "CCDC6, a tumor repressor known for its pro-apoptotic effects, undergoes SUMOylation, influencing its tumor-suppressive functions." (PMID 39457720, 2024). "We performed next-generation RNA sequencing on WCM271 tumor tissue and identified CCDC6 as the RET gene fusion partner." (PMID 35510953, 2022). "Francesco and colleagues presented evidence for the downregulation of CCDC6 protein enhancing tumor aggressiveness and reducing sensitivity to DNA damaging agents, such as cisplatinum, in patients with non-small cell lung cancer (NSCLC)." (PMID 36186907, 2022). "We observed an interesting phenomenon in the association between CCDC6 and the prognosis of patients with HCC, the survival of patients with CCDC6 positive expression got worse with higher tumor grades in the UALCAN analysis." (PMID 36186907, 2022). "We have reported a patient-derived iCCA xenograft mouse model endogenously expressing an FGFR2-CCDC6 fusion protein and produced preliminary evidence for the role of CCDC6 in tumor promotion." (PMID 36186907, 2022). "The high CCDC6 expression levels were significantly correlated with advanced tumor grades as well as poor prognosis in patients with HCC, but not in patients with CCA." (PMID 36186907, 2022). "In recent studies, evidence was found that the tumor-suppressive (pro-apoptotic) effects of CCDC6 were influenced by sumoylation." (PMID 35406382, 2022). "To further evaluate the effect of CCDC6 expression on the tumor microenvironment, we investigated these correlations using the established computational resource CIBERSORT." (PMID 36186907, 2022). "Due to gene translocations, somatic mutations, and altered protein levels, the tumour suppressor protein CCDC6 is known to lose its functional properties in several tumour types." (PMID 35964058, 2022). "As for patients with iCCA, the multivariate Cox regression analysis showed that CCDC6 expression, poor clinical state, and a large tumor diameter were correlated with a poor overall survival." (PMID 36186907, 2022). "The tumour suppressor CCDC6 is involved in HR repair by regulating the PP4c phosphatase activity on γH2AX." (PMID 35964058, 2022). "As expected, USP7 inhibitors (like P5091) can downregulate CCDC6 protein levels and favor tumor cells sensitivity to PARP inhibitors in non-small cell lung cancer, lung neuroendocrine cancer and hormone-sensitive and castration-resistant prostate cancer." (PMID 33967786, 2021). "The tumour suppressor CCDC6 is a ubiquitously expressed nuclear and cytosolic protein, phosphorylated at Serine 244 residue by ERK1/2 and able to induce apoptosis." (PMID 34841108, 2021). "CCDC6 is a tumour-suppressor and a pro-apoptotic protein involved in DNA damage response and repair." (PMID 32580154, 2020). "We report an adult patient with ATC and a biopsied tumor metastasis harboring a CCDC6-RET gene fusion who responded dramatically to LOXO-292, a highly selective RET inhibitor currently in clinical development." (PMID 32292131, 2020).
tumor (continued). "Because of its role in the surveillance of DNA integrity, CCDC6 has been proposed as a tumor suppressor gene." (PMID 31877762, 2019). "Of notice, the tumor suppressor DNA repair function of CCDC6 has been found lost, by several mechanisms, in many human cancer." (PMID 29455670, 2018). "For example, the combined treatment with diverse TKIs, including gefitinib, should target preferentially the tumour cells carrying CCDC6 rearrangements, while normal cells should be more resistant to the combination of these two drugs." (PMID 29455670, 2018). "A combination therapy of TKIs and PARPi should be valuable in lung or different cancer types that result defective for CCDC6 because of qualitative targeting of tumour over non-tumour cells." (PMID 29455670, 2018). "In the five iCCA patients with FGFR2 fusions (BICC1 (n=2), KIAA1217, TACC1, CCDC6), two confirmed PRs and a SD (25% tumour reduction) of 24–41 weeks duration were observed." (PMID 28972963, 2017). "In order to demonstrate a tumour suppressive role of the CCDC6 gene in vivo we first planned to generate a Ccdc6 null mice." (PMID 25970781, 2015). "CCDC6 gene product is a pro-apoptotic protein substrate of ATM, whose loss or inactivation enhances tumour progression." (PMID 25885523, 2015). "Additionally, the CCDC family of proteins, including CCDC67 or CCDC6, are known to play functional roles as tumor suppressors." (PMID 39823827, 2025). "In addition, we assessed correlations between CCDC6 expression and tumor-infiltrating immune cells using data from the TIMER and GEPIA databases." (PMID 36186907, 2022). "However, deeper exploration is necessary to Figure out the precise role of CCDC6 in the tumor-immune microenvironment." (PMID 36186907, 2022). "Overall, our results imply that assessing CCDC6 levels in tumours may provide critical information for therapy choices in HGSOC." (PMID 35964058, 2022). "Moreover, we found that the CCDC6 levels were positively correlated with the presence of tumor-infiltrating immune cells, including macrophages, CD4+T cells and dendritic cells." (PMID 36186907, 2022). "Our GSEA and GSVA results on the TCGA database analysis indicate that CCDC6 may be related to histone acetylation and the infiltrations of tumor immune cells in HCC." (PMID 36186907, 2022). "We found a gradual significant increase in the CCDC6 expression of patients with HCC according to their tumor grade (from 1, well differentiated; to 2, moderately differentiated; to 3, poorly differentiated; and to 4, undifferentiated) and in patients with in stage 2 CCA." (PMID 36186907, 2022). "Moreover, MiR146b-5p targets both the gene expression of RARβ and CCDC6 and promotes tumor development." (PMID 35186709, 2021). "Besides controlling AR and ARv7, USP7 is also in charge of the stability of the CCDC6 gene product, a tumor suppressor whose impairment induces a BRCAness-like phenotype which associates to PARP inhibitors sensitivity in prostate and urothelial cancer." (PMID 33546726, 2021). "Indeed, low levels of expression of CCDC6 protein and several CCDC6 fusions have been reported in many tumor types." (PMID 31877762, 2019). "By this approach, then, we could further stratify the G3 tumor category into two different groups based on the expression pattern of CCDC6 and USP7." (PMID 30786932, 2019). "Then, we have compared the CCDC6/USP7 expression scores to the tumor grade." (PMID 30786932, 2019). "The important role of CCDC6 in the DNA damage could impact genome stability in primary tumours, as reported also for other genes whose products participate in DDR and are commonly deregulated or inactivated in tumors." (PMID 29455670, 2018). "This suggests that tumours with defective CCDC6 signaling could be sensitive to the combination of DNA-damaging and anti-mitotic drugs." (PMID 29455670, 2018). "However, the patient developed a resistant tumor with the same histological features and a CCDC6-RET fusion (C1;R12) at 38 weeks." (PMID 29434222, 2018).